SMARCB1 (SWI/SNF related BAF chromatin remodeling complex subunit B1)
Diseases named in the same sentence as SMARCB1 in open-access papers (continued):
Sharing a sentence is not in itself a finding about the gene and the disease.
medulloblastoma (18 papers, 2013 to 2025). A malignant, invasive embryonal neoplasm arising from the cerebellum. "We report concurrent IDH1 and SMARCB1 mutations in a medulloblastoma patient." (PMID 29971034, 2018). "Altogether, these results converge to split our intracranial tumours in two distinct entities, one clustering with extracranial Smarcb1-deficient tumours, and the other clustering close to tumours of neuronal origin, that is, medulloblastomas and neuroblastomas." (PMID 26818002, 2016). "This feature is highly specific for AT/RTs in pediatric neuro-oncology; the loss of SMARCB1 expression in immunohistochemistry strongly supports the diagnosis of AT/RT rather than medulloblastoma or choroid plexus carcinoma." (PMID 27095948, 2016). "Notably, the basal expression levels of SMARCB1 were low in SMARCB1-competent cancers, such as glioblastoma and medulloblastoma." (PMID 27095948, 2016). "Interestingly, the knockdown of SMARCB1 in glioblastoma and medulloblastoma generated little effect on the LIN28B levels and the expression of CCND1 and CDKN1C." (PMID 27095948, 2016). "Immunohistochemistry with antibodies against Ini1/Smarcb1, Lin28, EMA, and cytokeratin is very helpful in this regards since medulloblastomas lack loss of Ini1 and do not show expression of the other antigens." (PMID 27781424, 2016). "As a comparison, we assessed two medulloblastoma cases (NMB361 and NMB795), which showed nuclear staining for SMARCB1 and were negative for both PDGFRα and FGFR1." (PMID 27783942, 2016).
melanoma (18 papers, 2012 to 2025). A malignant, usually aggressive tumor composed of atypical, neoplastic melanocytes. "A remaining gap is our understanding of why mutations in genes encoding some SWI/SNF subunits, particularly ARID2, are over-represented in melanoma compared to mutations in genes encoding other subunits with known tumor-suppressor functions such as SMARCB1." (PMID 35323214, 2022). "Six of these neoplasms were located in the pancreas and included Ewing sarcoma, SMARCB1(INI1)-deficient neoplasms, melanoma, and sclerosing epithelioid sclerosing neoplasms." (PMID 34647171, 2022). "However a different study challenged this finding and it has recently been reported that loss of SMARCB1 results in senescence by suppressing SOX10 expression in melanoma cells." (PMID 35323214, 2022). "Further studies are needed to determine which EZH2 or SMARCB1 alterations are most predictive of response to EZH2-targeted therapies and the best administration sequence of these drugs in EZH2-mutated melanomas." (PMID 39984702, 2025). "Immunohistochemistry on patient-derived melanoma samples indicated there is significantly lower SMARCB1 expression in late stage primary and metastatic melanoma, correlating with poorer patient survival and increased resistance to chemotherapeutics." (PMID 35323214, 2022). "SMARCB1 is a core component of cBAF and PBAF complexes which has been implicated in melanoma and other cancers." (PMID 35323214, 2022). "A screen identified SMARCB1 as a factor required for mutant BRAF-induced senescence, suggesting a tumor suppressor role for SMARCB1 in melanomas that harbor this oncogene." (PMID 35323214, 2022). "The regulation of a melanocyte-specific factor like SOX10 by SMARCB1 indicates that SMARCB1 likely is essential for survival of the melanocyte lineage and in melanoma." (PMID 35323214, 2022). "However, it must be noted that many poorly differentiated neoplasms have also been shown to exhibit distinct neuroendocrine differentiation, such as SMARCA4- or SMARCB1-deficient cancers, NUT cancers, melanoma and others." (PMID 39049067, 2024). "Therefore, it is somewhat surprising that SMARCB1 is not more frequently mutated in melanoma." (PMID 35323214, 2022). "Although SMARCA4 and SMARCB1 are also required for SWI/SNF-mediated chromatin remodeling at lineage-specific enhancers, loss of these subunits may be inconsistent with melanocyte and melanoma viability under most contexts due to their broader role in the regulation of gene expression." (PMID 35323214, 2022). "Interestingly, SMARCB1-depleted melanoma cells were more resistant to BRAF inhibitors but more sensitive to BCL2 inhibitors, providing additional evidence that SMARCB1 expression can influence sensitivity to therapeutics." (PMID 35323214, 2022). "ALCL is negative for cytokeratins, vascular markers, melanoma markers, TFE3, and retains the expression of INI1/SMARCB1." (PMID 34572893, 2021).
myoepithelial carcinoma (16 papers, 2013 to 2025). "Additional immunohistochemical markers such as GFAP, which may be positive in myoepithelioma/myoepithelial carcinoma, and SMARCB1, which may show mosaic loss specifically in OFMT, are useful for such differential diagnosis." (PMID 40151688, 2025). "An atypical teratoid rhabdoid tumor (TH03_0016_S01) and myoepithelial carcinoma (TH03_0113_S01) harbored loss of SMARCB1 (OMIM 601607) (INI1) through a frameshift mutation or protein loss of unknown mechanism detected by immunohistochemistry, respectively." (PMID 31651965, 2019). "Previously, SMARCB1-deficient myoepithelial carcinoma of soft tissue was reported to have an EWSR1 gene rearrangement located on the same chromosome 22 as SMARCB1 without SMARCB1 gene abnormalities." (PMID 38836164, 2024). "SMARCB1 loss is known to occur in a subset of myoepithelial carcinomas lacking gene fusions." (PMID 39636306, 2025). "The original diagnosis in most cases of SMARCB1-deficient SNAC was HG non-ITAC and less frequently HG myoepithelial carcinoma or HG ITAC." (PMID 38085333, 2024). "Our cases were entirely negative for S100 and SOX10, which, in combination with SMARCB1, negativity excludes myoepithelial carcinoma." (PMID 38085333, 2024). "Based on histological pattern, SMARCB1-deficient carcinoma has been previously likely included in the historical spectrum of SNUC, basaloid nonkeratinizing SCC or myoepithelial carcinoma." (PMID 35307773, 2022).
renal cell carcinoma (16 papers, 2016 to 2026). "No hemoglobinopathies were identified in the patient, in this context, the neoplasm is appropriately classified as unclassified renal cell carcinoma (RCC) with medullary phenotype and SMARCB1 deficiency." (PMID 40777608, 2025). "Given its high aggressiveness, unclassified renal cell carcinoma (RCC) with medullary phenotype and SMARCB1 deficiency presents a poor prognosis, with a survival of four months for patients with metastases and seventeen months for those without metastases." (PMID 40777608, 2025). "Thus, due to the absence of hematological alterations and distinct epidemiological profile, the neoplasm is appropriately classified as unclassified renal cell carcinoma (RCC) with medullary phenotype and SMARCB1 deficiency." (PMID 40777608, 2025). "In summary, both Xp11.2-associated translocation and the loss of SMARCB1 expression in renal cell carcinoma are rare and have not previously been reported." (PMID 27733182, 2016). "As for renal cell carcinoma VCL-ALK, it also occurs in patients with sickle cell trait and histological findings compatible with RMC, however, there is no deficiency of SMARCB1 expression." (PMID 40777608, 2025). "Clinica, histopathological and molecular characteristics of the 12 cases of Unclassified renal cell carcinoma (RCC) with medullary phenotype and SMARCB1(INI1) deficiency and no hemoglobinopathy described in the literature." (PMID 40777608, 2025). "Diagnostically, patients with RMC are often misdiagnosed with renal cell carcinoma (RCC) due to the rarity of RMC, the lack of access to SMARCB1 histological stains and unknown sickle cell status." (PMID 30860482, 2019).
rhabdoid tumor of the kidney (15 papers, 2015 to 2026). A rhabdoid tumor that arises from the kidney. "Based on their similar background of SMARCB1 loss, as has already been stated, RMCs and rhabdoid tumors of the kidney (RTK) share a similar gene expression signature, which is distinct from other renal tumors." (PMID 36291828, 2022). "Deletions and mutations of the hSNF5/INI1/SMARCB1 locus at 22q11.2 were demonstrated in AT/RTs as well as in rhabdoid tumors of the kidney and extra-renal sites." (PMID 25934090, 2015). "In addition to RMC, SMARCB1 alterations are found in approximately 20% of all cancers, and biallelic inactivation of SMARCB1 is also a universal characterizing feature of kidney malignant rhabdoid tumor (MRT) that similarly has an extremely low rate of mutation and aggressive nature of onset." (PMID 35837094, 2022). "Originally recognized as a distinct entity following cytogenetic identification of monosomy 22 in renal Rhabdoid Tumors, AT/RT now encompasses CNS tumors characterized by SMARCB1 (INI-1) or SMARCA4 (BRG-1) alterations within the SWI/SNF chromatin-remodeling complex." (PMID 41374972, 2025). "It is noteworthy that SMARCB1 aberrations also occur in non-RMC and non-rhabdoid kidney tumors." (PMID 36291828, 2022).
embryonal tumors (14 papers, 2015 to 2025). "ATRTs are highly aggressive embryonic tumors primarily encountered in children with mutations in SMARCB1 as the main genetic hallmark." (PMID 37221626, 2023). "Cribriform neuroepithelial tumor is a rare embryonal tumor characterized by loss of SMARCB1/INI1 but distinct from AT/RT by epigenetic features and clinical behavior." (PMID 36617415, 2023). "This loss of INI1 (SMARCB1) expression was a key finding in the diagnosis of ATRT, which is an aggressive and highly malignant embryonal tumor." (PMID 40851939, 2025). "CNS embryonal tumors with EWSR1-PLAGL1 rearrangements acquire or include a population of cells with SMARCB1 alterations that are the component that predominate at relapse, suggesting treatment aimed at this disease component at diagnosis should be considered." (PMID 38639853, 2024). "There are multiple examples of embryonal tumors that contain LOF mutations in the SWI/SNF pathway, such as AT/RT, CRINET, and medulloblastoma; however, bi-allelic loss of SMARCB1 in AT/RT has been the most well-characterized example." (PMID 37173979, 2023). "Due to the clear involvement of both SWI/SNF LOF and resultant ERV expression in AT/RT, it is likely this phenomenon may also occur in other embryonal tumors with SMARCB1 or other SWI/SNF gene LOF, and these complex relationships should be further explored in future studies." (PMID 37173979, 2023).
malignant peripheral nerve sheath tumor (14 papers, 2013 to 2025). Malignant peripheral nerve sheath tumor (MPNST) is a rare and often aggressive soft tissue sarcoma occurring in a wide range of anatomical sites. "Approximately 40% of cases demonstrate loss of SMARCB1 (INI1) expression, and rare tumors may progress to epithelioid malignant peripheral nerve sheath tumor." (PMID 41300852, 2025). "Malignant peripheral nerve sheath tumors (MPNSTs) are commonly associated with poor prognosis and are primarily caused by germline mutations in the SMARCB1/INI-1 gene." (PMID 37305741, 2023).
colorectal cancer (12 papers, 2013 to 2024). A primary or metastatic malignant neoplasm that affects the colon or rectum. "In a study that analyzed 3,051 cases of colorectal carcinoma, SMARCB1 loss was detected in only 0.46% of the cases." (PMID 36732357, 2023). "We hypothesize some correlation between BRAF mutation and SMARCB1-defcient features in colorectal cancers." (PMID 38217014, 2024). "Moreover, we discuss the role of SMARCB1 alterations in diagnosis and treatment and predictive markers of potential targeted therapy or immunotherapy of colorectal cancer (CRC)." (PMID 38217014, 2024). "To determine the effects of SP-2577 on SWI/SNF-mutant cell viability, we performed drug-dose-response (DDR) studies with 72 h CellTiterGlo viability endpoints in SCCOHT (SMARCA4-/-), OCCC (ARID1A-/-), lung (SMARCA4-/-), kidney (SMARCB1-/-), and colorectal cancer cell lines (SMARCA4-/-)." (PMID 32649682, 2020). "In order to shed light on the biological role of SMARCB1/INI1, in this study we investigated its expression profile and evaluated the relationship between molecular alterations and clinico-histological markers of dedifferentiated and aggressive colorectal carcinomas." (PMID 24286138, 2013). "Although SMARCB1/INI1 is the most extensively studied subunit of the SWI/SNF complex, very little is known about its role in the pathogenesis of colorectal cancer (CRC)." (PMID 24286138, 2013). "Negative SMARCB1/INI1 expression is quite rare in epithelial tumors and none of the studies published so far has addressed its role in colorectal cancer." (PMID 24286138, 2013).
soft tissue sarcoma (12 papers, 2013 to 2025). A malignant neoplasm arising from muscle tissue, adipose tissue, blood vessels, fibrous tissue, or other supportive tissues excluding the bones. "ES is a rare soft tissue sarcoma that is characterized by the loss of expression in INI1/SNF5/SMARCB1." (PMID 33879235, 2021).
Intellectual disability (11 papers, 2019 to 2026). "A recurrent missense pathogenic variant in the N-terminal part of SMARCB1 causes severe intellectual disability and choroid plexus hyperplasia with resultant hydrocephalus, termed ID-CPH." (PMID 40794298, 2025). "The pathogenic de novo missense SMARCB1 variant (c.110G > A; p.Arg37His) identified in four patients with severe intellectual disability, choroid plexus hyperplasia and resultant hydrocephalus termed ID-CPH is located within exon 2 of SMARCB1, encoding the winged-helix DNA-binding domain (WHD)." (PMID 40794298, 2025). "Impaired SMARCB1 function may also disturb neurite outgrowth and synapse formation in humans causing intellectual disability in patients with neurodevelopmental disorders such as CSS." (PMID 40794298, 2025). "Further, the recurrent SMARCB1-R37H mutation in the winged-helix DNA-binding domain, which causes severe intellectual disability and Kleefstra-like syndrome, also demonstrated hydrogen bonding with the carbonyl backbone of ARID1A-L2073 and Y2076 that is likely disrupted upon mutation." (PMID 37500730, 2023). "SMARCB1 gene and 22q11.2 recurrent region (distal type I,D-E/F) in the fragment have sufficient evidence for haploinsufficiency, which are associated with clinical phenotypes such as global developmental delay, intellectual disability, cleft lip, and behavioral problems." (PMID 35719402, 2022). "Pathogenic variants in SMARCB1 generally cause a very severe CSS phenotype with global developmental delay and in most instances, severe intellectual disability." (PMID 40794298, 2025). "Patients with germline SMARCB1 PVs and neurodevelopmental disorders do not usually develop SMARCB1-deficient tumours but instead exhibit severe intellectual disability and congenital malformations." (PMID 40794298, 2025). "Impaired SMARCB1 function could disturb neurite outgrowth and synapse formation and may lead to intellectual disability." (PMID 37219662, 2023). "The functional impairment of the SMARCB1 protein or other BAF complex subunits during neural differentiation may either lead to aberrant proliferation and tumorigenesis or intellectual disability and developmental delay." (PMID 40794298, 2025). "In turn, severe intellectual disability is not observed in patients with SMARCB1-related SWN or in carriers of germline SMARCB1 PVs in RTPS1 families." (PMID 40794298, 2025).
mesenchymal neoplasms (11 papers, 2021 to 2025). "Another crucial immunohistochemical finding was the expression of SMARCB1 (INI1) in a mosaic pattern (20× magnification), which is a known characteristic in certain mesenchymal neoplasms and provides an additional diagnostic clue." (PMID 40361436, 2025). "SMARCB1 deficiency has been mainly described in mesenchymal tumors, but next-generation sequencing studies have subsequently shown that SMARCB1 alterations are also found in a subset of carcinomas, although at low frequency." (PMID 35864317, 2022). "SWI/SNF complex-deficient carcinomas and mesenchymal tumors commonly share a discohesive epithelioid or rhabdoid morphology and this should guide the use of markers such as INI1 (SMARCB1) and BRG1 (SMARCA4) in the diagnostic work-up." (PMID 35864317, 2022). "Complete loss of INI1 (SMARCB1) expression has been linked to a number of pediatric and adult mesenchymal tumors." (PMID 35864317, 2022). "CD34 is useful to distinguish CCS from Epithelioid neoplasms with SMARCB1 and SMARCA4 deficiency or Mesenchymal tumors with NTRK fusions which are positive for CD34." (PMID 33478436, 2021). "As highlighted by Reference, carcinomas and mesenchymal tumors with SWI/SNF dysfunction frequently exhibit a discohesive epithelioid or rhabdoid phenotype, necessitating a targeted immunohistochemical evaluation of INI-1 (SMARCB1) and BRG1 (SMARCA4) during diagnostic workup." (PMID 40291911, 2025). "MELTVR is a rare mesenchymal tumor without expression of INI1/SMARCB1, usually occurring in adult women." (PMID 39872225, 2025).
pancreatic cancer (11 papers, 2019 to 2025). "However, it’s noteworthy that in SMARCB1-deficient undifferentiated pancreatic carcinoma, KRAS is typically wild-type, as reported in a recent study." (PMID 39777351, 2024). "On tissue NGS of immunotherapy-treated, SWI/SNF-altered pancreatic cancer patients, 7 patients harbored an ARID1A alteration (77%); 2 harbored an ARID1B mutation (22%); 3 harbored a SMARCA4 mutation (33%); 1 harbored a SMARCB1 mutation (11%); and 1 harbored a PBRM1 mutation (11%)." (PMID 34375311, 2021). "However, despite the loss of SWI/SNF protein complex is mainly associated with rhabdoid features, the loss of SMARCB1 is observed only in 5% of cases, none of which were pancreatic cancer." (PMID 33266496, 2020). "The previous reports, together with this study, indicate that PBRM1, ARID1A, and SMARCB1 play tumor-suppressive roles and inhibit EMT in pancreatic cancer." (PMID 40454484, 2025). "In summary, the current analysis suggests that a subgroup of patients with pancreatic cancer and alterations in SWI/SNF complex chromatin remodeling genes, such as ARID1A, ARID1B, PBRM1, SMARCA4, and SMARCB1, can respond to ICI." (PMID 34375311, 2021).
rhabdomyosarcoma (11 papers, 2013 to 2025). A rare aggressive malignant mesenchymal neoplasm arising from skeletal muscle. "To test this approach, we carried out a proof-of-concept study using EZH2 as a target for knockout in SMARCB1-negative (G-401) MRT cell line and SMARCB1-wild type (RD) rhabdomyosarcoma cell line; the former but not latter are sensitive to inhibition of EZH2." (PMID 26578851, 2015).